SIRT6 (sirtuin 6)
Diseases named in the same sentence as SIRT6 in open-access papers (continued):
Sharing a sentence is not in itself a finding about the gene and the disease.
Impaired glucose tolerance (1 paper, 2017). An abnormal resistance to glucose, i.e., a reduction in the ability to maintain glucose levels in the blood stream within normal limits following oral or intravenous administration of glucose. "Another study has demonstrated that high-fat diet fed SIRT6 overexpressing mice were protected from impaired glucose tolerance and fat accumulation." (PMID 28928419, 2017).
infarct (1 paper, 2023). "In addition, knockdown of Sirt6 generates a larger cerebral infarct size, again revealing a neuro-protective function of Sirt6." (PMID 37497437, 2023).
intestinal tumors (1 paper, 2022). "Together, these data support a role for SIRT6 in regulating the number of TICs in intestinal tumors." (PMID 35314684, 2022).
invasive breast carcinoma (1 paper, 2023). A carcinoma that infiltrates the breast parenchyma. "Of note, a cohort of 26 invasive breast cancer patients, which represents about 18.8% and 3.4% of the total SIRT6 and ERBB2 gene amplifications, respectively, harbors a concomitant gene amplification of both SIRT6 and ERBB2." (PMID 38081972, 2023).
laminopathy (1 paper, 2018). A rare genetic disorder caused by mutations in genes encoding proteins of the nuclear lamina.
leukopenia (1 paper, 2016). "Moreover, analysis of primary and peripheral lymphoid organs revealed leukopenia, as has been reported in other progeroid mouse models including SirT6−/− mice." (PMID 27225932, 2016).
lung diseases (1 paper, 2023). "SIRT6 exerts pivotal activities in the process of lung diseases, but whether SIRT6 impacts ALI has not been covered." (PMID 36988243, 2023).
microcephaly (1 paper, 2021). A congenital or acquired developmental disorder in which the circumference of the head is smaller than normal for the person's age and sex. "Also, in primates, the effect of Sirt6 loss in brain development is very evident, causing microcephaly and retardation of brain growth." (PMID 34720996, 2021). "Notably, the fetuses presented severe defects in head development, reduced head circumference, and microcephaly, which again points out the role of Sirt6 to ensure the proper development and differentiation of neural cells." (PMID 34720996, 2021).
mucinous carcinoma of the ovary (1 paper, 2018). "In addition, although the number of cases of mucinous carcinomas was limited, our results suggest that the expression patterns of SIRT6 and active β-catenin as possible prognostic indicators of mucinous carcinoma of the ovary." (PMID 30524965, 2018).
mucinous carcinomas (1 paper, 2018). "In 20 mucinous carcinomas, Nu-SIRT6 expression and Cy-Aβ-catenin expression were significantly associated with both OS and RFS." (PMID 30524965, 2018).
muscular dystrophy (1 paper, 2022). Muscular dystrophy (MD) refers to a group of more than 30 genetic diseases characterized by progressive weakness and degeneration of the skeletal muscles that control movement. "Increased levels of H3K56ac in muscle-specific Sirt6 mutants resulted in increased expression of Utrn, which compensates to a certain degree for the absence of dystrophin in mdx mice, thereby reducing damage of myofibers and partially ameliorating muscular dystrophy." (PMID 35859073, 2022). "Importantly, deletion of Sirt6 in Utrn−/−/mdx mutant mice did not reduce Evan’s blue uptake demonstrating that upregulation of Utrn due to the absence of SIRT6-mediated repression is critical for improvement of the muscular dystrophy phenotype in mdx mice." (PMID 35859073, 2022).
nasal polyps (1 paper, 2022). "In addition, nasal polyp tissues exhibit a decrease in SIRT6 expression and an increase in lactate dehydrogenase and Beclin1 expression." (PMID 35620467, 2022). "The overexpression of SIRT6 in primary fibroblasts extracted from nasal polyps inhibited the expression of lactate dehydrogenase (LDH), and hypoxia may promote the formation of nasal polyps by promoting autophagy of nasal polyp fibroblasts." (PMID 35620467, 2022). "Furthermore, the upregulation of SIRT6 gene expression in nasal mucosal epithelial cells can inhibit the migration of high mobility group protein 1 (HMGB1) induced by lipopolysaccharide (LPS), suggesting that SIRT6 may inhibit the development of nasal polyps by altering inflammatory processes." (PMID 35620467, 2022).
neutropenia (1 paper, 2026). A decrease in the number of neutrophils found in the blood. "In this study, a biomimetic nanozyme V-MDL-800 was constructed by coordinating Vanadium Single-atom enzymes (V/SAE) and the allosteric activator MDL-800 of Sirt6, and encapsulated into NM@V-MDL-800 with neutropenia cell membrane (NM)." (PMID 41624511, 2026).
non-melanoma skin carcinoma (1 paper, 2017). "Thus, our data appears to be consistent with the pro-proliferative function of SIRT6 as seen in prostate and non-melanoma skin cancer." (PMID 29234488, 2017).
obstructive sleep apnea (1 paper, 2022). "In this regard, three recent papers report reduced levels of klotho or SIRT6 in obstructive sleep apnea or in patients with interstitial lung abnormalities." (PMID 34958949, 2022).
osteonecrosis (1 paper, 2022). A none disease characterized by death of bone tissue due to a lack of blood supply. "The expression of SIRT6 in the osteonecrosis area of the femoral head decreased in GIONFH rats." (PMID 36275897, 2022). "Overexpression of SIRT6 can protect the activity of osteoblasts, promote osteoblastic differentiation, and reduce the damage of vascular endothelium, thereby preventing the occurrence of osteonecrosis of the femoral head." (PMID 36275897, 2022). "The aim of this study was to investigate the role of SIRT6 in the maintenance of bone tissue morphology and structure, intravascular lipid metabolism, and its potential molecular mechanism in glucocorticoid-induced osteonecrosis of the femoral head." (PMID 36275897, 2022). "SIRT6 can inhibit the occurrence of ferroptosis, reduce the damage of vascular endothelium, and promote osteogenic differentiation, so as to prevent the occurrence of osteonecrosis of the femoral head." (PMID 36275897, 2022). "In summary, SIRT6 can inhibit the occurrence of ferroptosis, reduce the damage of vascular endothelium, and promote osteogenic differentiation, thereby preventing the occurrence of osteonecrosis of the femoral head." (PMID 36275897, 2022).
ovarian cystadenocarcinoma (1 paper, 2022). An adenocarcinoma that arises from the ovary and is characterized by the presence of cystic structures. "Human protein atlas data also revealed significantly enhanced expression of SIRT6 in ovarian cystadenocarcinoma with strong intensity and nuclear localization." (PMID 35686673, 2022).
parasite infection (1 paper, 2024). "Therefore, SIRT6 in epithelial cells plays a protective role in gut inflammation and parasite infection." (PMID 39253083, 2024).
peripheral nerve injury (1 paper, 2021). Injury to a peripheral nerve. "Overall findings of the present study suggested that SIRT6 regulates migration, phagocytosis and M1/M2 polarization, thus affects functional recovery and nerve regeneration after peripheral nerve injury." (PMID 34906231, 2021). "Given the prominent role of macrophages in peripheral nerve recovery, we aim to investigate the role of SIRT6 in the regulation of phenotypes shift and functions in macrophages after peripheral nerve injury." (PMID 34906231, 2021).
Peritoneal Fibrosis (1 paper, 2024). Disorder characterized by a wide range of structural changes in PERITONEUM, resulting from fibrogenic or inflammatory processes. "The role of SIRT6 in PD-associated peritoneal fibrosis warrants further investigation." (PMID 38483736, 2024). "Therefore, we investigated the relationship between SIRT6 and peritoneal function and peritoneal fibrosis." (PMID 38483736, 2024). "The decrease in SIRT6 levels may be involved in the process of peritoneal fibrosis." (PMID 38483736, 2024). "In our next step, we plan to further study the cell signaling transduction of SIRT6 in MMT of HPMCS, and verify the relationship between SIRT6 and peritoneal fibrosis and MMT in an animal model of peritoneal fibrosis." (PMID 38483736, 2024). "Therefore, we speculate that SIRT6 inhibits peritoneal fibrosis by inhibiting MMT in PMCs." (PMID 38483736, 2024). "It is not yet known whether SIRT6 can affect peritoneal fibrosis and thus affect peritoneal function." (PMID 38483736, 2024).
peritonitis (1 paper, 2024). Inflammation of the peritoneum (tissue that lines the abdominal wall and covers most of the organs in the abdomen). "The interaction between peritoneal dialysis time and history of peritonitis on SIRT6 levels is statistically significant (P = 0.049)." (PMID 38483736, 2024). "We collected 110 PD patients with a duration of PD for more than 3 months and studied the influence of PD duration and history of peritonitis on SIRT6 levels in PD effluents (PDEs)." (PMID 38483736, 2024). "Patients with the PD duration of more than 5 years and a history of peritonitis had the lowest SIRT6 levels." (PMID 38483736, 2024). "Research has found that patients with a history of peritonitis and peritoneal dialysis lasting for more than 5 years have the most significant decrease in SIRT6 levels in PDEs." (PMID 38483736, 2024). "With the prolongation of peritoneal dialysis, the decrease in SIRT6 levels is more pronounced in patients with a history of peritonitis." (PMID 38483736, 2024). "The trend of changes in levels of SIRT6, E-cadherin, vimentin, and TGF-β1 indicates that prolonged dialysis time and a history of peritonitis lead to a decrease in SIRT6 and changes in MMT in peritoneal mesothelial cells." (PMID 38483736, 2024). "Patients with a history of peritonitis had lower SIRT6 and E-cadherin levels than those without such a history." (PMID 38483736, 2024). "Compared with the group without a history of peritonitis, the protein and gene levels of vimentin and TGF-β1 in the group with a history of peritonitis were significantly increased, while the protein and gene expression levels of SIRT6 and E-cadherin were significantly reduced (P < 0.05)." (PMID 38483736, 2024).
post-traumatic stress disorder (1 paper, 2018). An anxiety disorder precipitated by an experience of intense fear or horror while exposed to a traumatic (especially life-threatening) event. "Dysregulation of conditioned fear responses are involved in post-traumatic stress disorder (PTSD), hence the selective enhancement of negative memory of SIRT6 cKO mice suggests that reduced SIRT6 activity may be implicated in the disorder." (PMID 30189861, 2018).
postmenopausal osteoporosis (1 paper, 2025). Metabolic disorder associated with fractures of the femoral neck, vertebrae, and distal forearm. "SIRT6 can activate the SIRT6-ERα-FasL axis, promote OC apoptosis, reduce bone resorption, and alleviate the damage of OS to postmenopausal osteoporosis." (PMID 40427485, 2025).
primary hypertension (1 paper, 2023). "Therefore, attempts to connect Sirt6 with primary hypertension didn’t seem to be easy, and more research are urged to delve into this field." (PMID 37497437, 2023).
renal carcinoma (1 paper, 2025). A carcinoma arising from the epithelium of the renal parenchyma or the renal pelvis. "Furthermore, the identification of USP48 as a stabilizer of oncogenic SIRT6 expands the landscape of druggable deubiquitinating enzymes in renal cancer." (PMID 41354870, 2025).
retinitis pigmentosa (1 paper, 2020). Retinitis pigmentosa (RP) is an inherited retinal dystrophy leading to progressive loss of the photoreceptors and retinal pigment epithelium and resulting in blindness usually after several decades. "In addition, enhancement of glycolysis via SIRT6 inhibition was shown to promote survival of photoreceptor and to preserve vision in a mouse model of retinitis pigmentosa." (PMID 32736564, 2020).
sarcopenia (1 paper, 2025). Progressive decline in muscle mass due to aging which results in decreased functional capacity of muscles. "Moreover, a strong correlation between SIRT6 and FOXO1 (r=0.82, p<0.001) mRNA levels was observed in the group of patients with sarcopenia, in contrast to the geriatric controls (r=0.35, p=0.089)." (PMID 40034697, 2025). "The hypothesis is that genes involved in epigenetic modifications, such as SIRT1, SIRT3, SIRT6, FOXO1, FOXO3A, DNMT3A, and ELAVL1, are critical for the development of sarcopenia and could be used as biomarkers for the diagnosis and monitoring of the disease." (PMID 40034697, 2025). "Furthermore, we observed increased expression of SIRT3, SIRT6, FOXO1, and ELAVL1 in patients with sarcopenia compared to the geriatric controls and the frailty group, although these differencesdid not reach statistical significance." (PMID 40034697, 2025). "In patients suffering from sarcopenia, FOXO3A mRNA level did not correlate with other analyzed genes, while in the geriatric control group, FOXO3A expression correlated with the SIRT genes (SIRT1 r=0.56, p=0.004; SIRT3 r=0.48, p = 0.015; and SIRT6 r=0.58, p=0.002)." (PMID 40034697, 2025).
synovitis (1 paper, 2022). Inflammation of a synovial membrane. "Correlations between Sirt6 level and the modified Mankin scale and synovitis were observed." (PMID 36496445, 2022).
teratoma (1 paper, 2019). A non-seminomatous germ cell tumor characterized by the presence of various tissues which correspond to the different germinal layers (endoderm, mesoderm, and ectoderm). "Second, in terms of differentiation potential, Sirt6-null iPS-like cell has shown a bigger size of teratoma with some of typical three germ layer tissues and defects in embryonic body structure." (PMID 30630525, 2019). "To further identify the differentiation ability of Sirt6-null iPS-like cell line, we performed the teratoma formation experiment." (PMID 30630525, 2019). "This is different from the phenotype in Sirt6-null ES cells, with a smaller size of teratoma and normal shape of embryonic body structure." (PMID 30630525, 2019).
thrombotic disorders (1 paper, 2023). "Our study provides valuable insights into the intricate interplay between SIRT6 and platelet function, shedding light on potential therapeutic avenues for managing thrombotic disorders." (PMID 38186648, 2023).
tongue cancer (1 paper, 2021). A malignant neoplasm affecting the tongue. "Multiple studies have reported a correlation between survival rate and Sirt6 level in various cancers; in this study, the Sirt6-positive tongue cancer patients had a higher survival rate than the Sirt6-negative patients." (PMID 33727672, 2021).
tongue SCC (1 paper, 2021). "Among 97 tongue SCC patients, the Sirt6-positive patients exhibited a better prognosis than the Sirt6-negative patients." (PMID 33727672, 2021).
urinary system cancers (1 paper, 2025). "SIRT6 exerts diverse and context-dependent functions in urinary system cancers." (PMID 41463311, 2025).
viral myocarditis (1 paper, 2025). Myocarditis that is caused by an infection with a viral agent. "Sirtuin 6 (Sirt6) plays a critical role in cardiovascular pathophysiology, yet its involvement in viral myocarditis (VMC) remains poorly understood." (PMID 41466491, 2025).
tumor (234 papers, 2013 to 2026). "Many studies have reported increased Sirt6 expression and activity in many tumor tissues, and the expression level is inversely linked to overall patient survival." (PMID 41530841, 2026). "We thus suggest that the increase in Sirt6 activity caused by UBCS039 augmented Lao1 expression in macrophages to promote their polarization to the M2 type to favor tumor growth." (PMID 41530841, 2026). "Within the tumor microenvironment, loss of SIRT6 in TSPAN8+ cancer-associated fibroblasts (CAFs) drives a senescence-like phenotype, metabolic reprogramming, and secretion of pro-tumorigenic metabolites that foster chemoresistance." (PMID 41463311, 2025). "SIRT1, SIRT2, and SIRT7 have been implicated in the development and metastasis of EC, while SIRT6 has been shown to exhibit anti-tumor properties in this context." (PMID 41471349, 2025). "SIRT1 suppresses tumor growth by reducing inflammation and promoting oxidative metabolism, while SIRT6's role is controversial, linked to both oncogenic effects and tumor invasion." (PMID 40693828, 2025). "We also demonstrated that enhanced SUMOylation of SIRT6 mediated the anti-tumor effects induced by SENP1 deficiency in ESCC cells." (PMID 38954215, 2025). "SIRT6 also modulates tumor-associated processes indirectly by interacting with autophagy regulators such as ATG10 suggests a potential inhibitory role in GC progression." (PMID 41463311, 2025). "Isoforms such as SIRT1, SIRT2, and SIRT6 are mainly associated with tumor-suppressive activities, a function determined by their subcellular localization and the biochemical context of each cancer type." (PMID 41425553, 2025). "In line with its tumor-suppressive role, hepatic-specific SIRT6 knockout mice display increased susceptibility to both spontaneous and chemically induced liver tumors." (PMID 41463311, 2025). "To offer further insights into lipid accumulation leading to tumorigenesis, we used a leptin-deficient (obese) mouse model and found that loss of Sirt6 accelerates tumor formation in the liver, accompanlied by reduced CD4+ and CD8+ T cells in the liver." (PMID 38332150, 2024). "Sirt6 deficiency in the liver increases TG synthesis, providing a lipid-rich environment that promotes tumor formation." (PMID 38332150, 2024). "This dysregulation of the epigenetic program not only promotes tumor growth but also defines a distinct molecular subset of PDAC with reduced SIRT6 expression, linked to poor prognosis." (PMID 39682281, 2024). "It was demonstrated that the siRNA via the engineered extracellular vesicles caused the downregulation of the SIRT6 and blocked the metastasis and tumor growth." (PMID 37842237, 2023). "Loss of SIRT6 results in an increase in the number of intestinal stem cells (ISCs), which translates into enhanced tumor initiating potential in APCmin mice." (PMID 35314684, 2022). "Metabolic reprogramming upon SIRT6 loss induces tumour formation in the intestine but the mechanism is unclear." (PMID 35314684, 2022). "Mice injected with stable SIRT6-deficient cells (PC9/ER/shSIRT6) showed smaller tumor volumes than cells injected with PC9/ER/shCtrl." (PMID 35915188, 2022). "The TCGA dataset revealed that decreased SIRT6 was associated with a better overall survival in all 17 types of tumours, but with a worse overall survival in gastrointestinal cancer, which was consistent with meta-analysis results." (PMID 35172823, 2022). "Meanwhile, in this study, loss of SIRT6 expression was observed in tumor tissue compared with adjacent tissue and we found SIRT6 expression elevated significantly after inhibition of AKT." (PMID 35715817, 2022).